ENSG00000258674 (novel protein)
Gene: Protein-coding gene on chromosome 19 (19,516,227 to 19,536,076, forward strand). Ensembl gene ENSG00000258674.
Genetic constraint (gnomAD): Loss-of-function variants: 25 observed, 24.99 expected, observed/expected ratio (o/e) 1, 90% interval 0.73 to 1.4. Missense variants: 380 observed, 343.09 expected, observed/expected ratio (o/e) 1.11, 90% interval 1.02 to 1.21. Synonymous variants: 159 observed, 147.83 expected, observed/expected ratio (o/e) 1.08, 90% interval 0.94 to 1.23.